HNRNPA1 (heterogeneous nuclear ribonucleoprotein A1)
Description:
Involved in the packaging of pre-mRNA into hnRNP particles, transport of poly(A) mRNA from the nucleus to the cytoplasm and modulation of splice site selection. Plays a role in the splicing of pyruvate kinase PKM by binding repressively to sequences flanking PKM exon 9, inhibiting exon 9 inclusion and resulting in exon 10 inclusion and production of the PKM M2 isoform. Binds to the IRES and thereby inhibits the translation of the apoptosis protease activating factor APAF1. May bind to specific miRNA hairpins. (Microbial infection) May play a role in HCV RNA replication. (Microbial infection) Cleavage by Enterovirus 71 protease 3C results in increased translation of apoptosis protease activating factor APAF1, leading to apoptosis.
Synonyms: hnRNP A1; HNRPA1; hnRNP-A1; ALS20; ALS19; HNRPA1L3; IBMPFD3; MPD3; UP 1
Tractability: Small molecule: a structure with a bound ligand is known; it has a high-quality binding pocket; it belongs to a druggable protein family. PROTAC: UniProt records ubiquitination sites on it; ubiquitination databases record sites on it; its protein half-life has been measured; a small molecule that binds it is known.
Target class: Other nuclear protein
Gene: Protein-coding gene on chromosome 12 (54,280,193 to 54,287,088, forward strand). Ensembl gene ENSG00000135486.
Subcellular location: Nucleus; Cytoplasm
Subcellular location (Human Protein Atlas): Nucleoplasm
Pathways (Reactome):
Disease: Dengue Virus-Host Interactions; SARS-CoV-1 modulates host translation machinery; SARS-CoV-1-host interactions
Metabolism of RNA: Processing of Capped Intron-Containing Pre-mRNA; mRNA Polyadenylation; mRNA Splicing - Major Pathway
Signal Transduction: FGFR2 alternative splicing
Gene Ontology:
Molecular function: DNA binding; G-rich strand telomeric DNA binding; miRNA binding; pre-mRNA binding; protein binding; protein domain specific binding; RNA binding; single-stranded DNA binding; telomeric repeat-containing RNA binding; mRNA 3'-UTR binding; single-stranded RNA binding; nucleic acid binding
Biological process: cellular response to glucose starvation; cellular response to sodium arsenite; import into nucleus; negative regulation of telomere maintenance via telomerase; nuclear export; positive regulation of telomere maintenance via telomerase; regulation of alternative mRNA splicing, via spliceosome; regulation of RNA splicing; mRNA splicing, via spliceosome; RNA export from nucleus
Cellular component: catalytic step 2 spliceosome; cytoplasm; extracellular exosome; membrane; nucleoplasm; nucleus; ribonucleoprotein complex; spliceosomal complex; cytosol; synapse
Genetic constraint (gnomAD): Loss-of-function variants: 7 observed, 36.84 expected, observed/expected ratio (o/e) 0.19, 90% interval 0.11 to 0.36. The upper end of that interval is the gene's LOEUF score, 0.36, which puts it in group 1 of 6, group 1 being the genes least tolerant of losing a copy. Missense variants: 172 observed, 396.5 expected, observed/expected ratio (o/e) 0.43, 90% interval 0.38 to 0.49. Synonymous variants: 129 observed, 134.52 expected, observed/expected ratio (o/e) 0.96, 90% interval 0.83 to 1.11.
Homologues: Orthologues: chimpanzee HNRPA1LK1 (100% identical), macaque HNRNPA1 (100% identical), pig HNRNPA1 (100% identical), dog HNRNPA1 (99% identical), mouse Hnrnpa1 (86% identical), rat Hnrnpa1 (86% identical), zebrafish hnrnpa1b (65% identical). Paralogues in human: HNRNPA1L3 (85% identical), HNRNPA1L2 (83% identical), HNRNPA3 (73% identical), HNRNPA2B1 (61% identical), HNRNPA0 (35% identical), HNRNPD (30% identical), MSI2 (29% identical), MSI1 (28% identical), HNRNPDL (28% identical), DAZAP1 (27% identical), HNRNPAB (27% identical), NUCLEOLIN (26% identical), and 24 more.
Diseases named in the same sentence as HNRNPA1 in open-access papers:
HNRNPA1 is named in the same sentence as 154 diseases in open-access papers, as found by Europe PMC text mining. Sharing a sentence is not in itself a finding about the gene and the disease. The quoted sentences say what the papers report.
amyotrophic lateral sclerosis (65 papers, 2014 to 2026). Amyotrophic lateral sclerosis (ALS) is a neurodegenerative disease characterized by progressive muscular paralysis reflecting degeneration of motor neurons in the primary motor cortex, corticospinal tracts, brainstem and spinal cord. "Mutations of hnRNPA1 result in amyotrophic lateral sclerosis (ALS) and the syndrome multisystem proteopathy." (PMID 35215793, 2022). "Several hereditary diseases have also been linked to HNRNPA1 missense mutations, including multisystem proteinopathy and amyotrophic lateral sclerosis." (PMID 32086392, 2020). "Besides, another variant mapped to HNRNPA1 is associated with amyotrophic lateral sclerosis and inclusion body myopathy with Paget’s disease of bone and frontotemporal dementia." (PMID 38291454, 2024). "Moreover, it was revealed that PAD4 can competitively inhibit the methylation of some RGG motif proteins including the FET proteins (FUS, EWS and TAF15) and hnRNPA1, and each has been linked to amyotrophic lateral sclerosis (ALS)." (PMID 37778382, 2023). "Additionally, dysregulation of mRNA splicing contributes to neurodegenerative disorders associated with hnRNPA1, such as amyotrophic lateral sclerosis, frontotemporal lobar degeneration, Alzheimer’s disease, and spinal muscular atrophy." (PMID 37463443, 2023). "The demonstration that increased expression of HNRNPA1 recapitulates DM1 manifestations and splicing defects adds to a growing list of diseases attributed to HNRNPA1 misexpression and mutations, including Alzheimer’s disease (AD) and amyotrophic lateral sclerosis." (PMID 32086392, 2020). "Indeed, we have previously observed this effect when analysing mutations of human hnRNPA1 and hnRNPA2 prion-like proteins associated with multisystem proteinopathy and amyotrophic lateral sclerosis." (PMID 27686217, 2016). "Pathogenic mutation of heterogeneous nuclear ribonucleoprotein A1 (hnRNPA1) is causative to amyotrophic lateral sclerosis (ALS)." (PMID 40858193, 2025). "HNRNPA1 was originally associated with multisystem proteinopathy and amyotrophic lateral sclerosis (ALS)." (PMID 39017652, 2024). "Mutations in HNRNPA1 encoding heterogeneous nuclear ribonucleoprotein (hnRNP) A1 are a rare cause of amyotrophic lateral sclerosis (ALS) and multisystem proteinopathy (MSP)." (PMID 34291734, 2021). "hnRNPA1 is also involved in many other processes necessary for cellular function including proliferation, mRNA splicing, and telomerase activity, and mutations in hnRNPA1 have been associated with human diseases including amyotrophic lateral sclerosis 20, lung adenocarcinoma and HIV-1." (PMID 31010097, 2019). "Mutations of HNRNPA1 were reported in the motoneuron degeneration disorders Amyotrophic Lateral Sclerosis (ALS) and Frontotemporal Lobar Degeneration (FTLD)." (PMID 27034888, 2016). "Among these genes, HNRNPA1, HNRNPC, and HNRNPU are involved in RNA processing and have been linked to neurodegenerative diseases such as amyotrophic lateral sclerosis and frontotemporal dementia." (PMID 40943121, 2025). "Tau aggregates condensation via LLPS is similar to amyotrophic lateral sclerosis (ALS)-associated protein aggregates of Fused in Sarcoma (FUS), hnRNPA1, and TAR DNA-binding protein 43 (TDP43)." (PMID 39596399, 2024). "Here we analyse the amyloid formation mediated by condensation of the low-complexity domain of hnRNPA1, a protein involved in amyotrophic lateral sclerosis." (PMID 37749234, 2023). "We comparethe behavior of three different protein condensates, i.e., those formedby either hnRNPA1, FUS, or TDP-43 proteins, whose liquid-to-gel transitionsare associated with the onset of amyotrophic lateral sclerosis andfrontotemporal dementia." (PMID 37194953, 2023). "Genetic studies have shown that a single amino acid mutation in the GRD domain of HNRNPA1 and HNRNPA2 protein is related to the proteinopathy of multiple systems and amyotrophic lateral sclerosis." (PMID 33907500, 2021).
amyotrophic lateral sclerosis (continued). "In human multisystem proteinopathy and amyotrophic lateral sclerosis (ALS), mutations in the prion-like domains of hnRNPA2B1 and hnRNPA1 occur." (PMID 32905346, 2020). "Mutations in fused-in-sarcoma RNA-binding protein (FUS) and in heterogeneous nuclear ribonucleoprotein A1 (hnRNPA1) are involved in familial forms of amyotrophic lateral sclerosis (ALS) and frontotemporal dementia (FTD)." (PMID 33260713, 2020). "Notably, hnRNPA1 mutations found in familial amyotrophic lateral sclerosis (ALS) and multisystem proteinopathoy (MSP) are all involved in the fibril core and contribute to fibril stability." (PMID 33311513, 2020). "Defects of HNRNPA1 could also cause aging-related diseases, such as amyotrophic lateral sclerosis (ALS) and Alzheimer’s disease." (PMID 31257225, 2019). "In this context, it would be intriguing to note that a number of paraspeckle-enriched RBPs with IDRs, including SFPQ, FUS, EWSR1, TAF15, TDP-43, SS18L1 and HNRNPA1, are mutated in familial cases of amyotrophic lateral sclerosis (ALS) and other neurodegenerative diseases." (PMID 30355755, 2018). "Some paraspeckle proteins, such as TDP-13, FUS, EWS, TAF15, HNRNPA1, SS18L1, and SFPQ have been associated with neuro-degenerative diseases, such as amyotrophic lateral sclerosis (ALS) and frontotemporal dementia (FTD)." (PMID 30087896, 2018). "Aggregation of many RBPs, such as TIA-1, FUS, TDP43, hnRNPA1 and hnRNPA2 in Amyotrophic lateral sclerosis/frontotemporal dementia (ALS/FTD) proteinopathies are mediated by prion-related domain (PRD)." (PMID 30367664, 2018). "A conspicuous number of RNA binding proteins (RBPs) have been shown to be associated with amyotrophic lateral sclerosis (ALS) or other neuromuscular diseases: for example, mutations in RBPs such as hnRNPA1 and A2B1, TDP-43, and FUS are associated with ALS." (PMID 28082869, 2016). "Interestingly, mutations of HNRNPA1 and HNRNPA2B1 are identified in families of multisystem proteinopathy or amyotrophic lateral sclerosis." (PMID 36831269, 2023). "Mutations affecting several RBPs, including FUS, TDP-43, hnRNPA1, hnRNPA2B1, matrin-3, and TIA1, are linked to amyotrophic lateral sclerosis (ALS), frontotemporal dementia (FTD), multisystem proteinopathy (MSP), and hereditary inclusion body myopathy (hIBM) phenotypes." (PMID 34291734, 2021). "Genetic analyses of patients with amyotrophic lateral sclerosis (ALS) have revealed a strong association between mutations in genes encoding many RNA-binding proteins (RBPs), including TARDBP, FUS, hnRNPA1, hnRNPA2B1, MATR3, ATXN2, TAF15, TIA-1, and EWSR1, and disease onset/progression." (PMID 32547363, 2020). "Loss of frontotemporal dementia/amyotrophic lateral sclerosis (FTD/ALS)-associated RBPs TDP-43 and hnRNPA1 lead to distinct alterations in the neuritic proteome and transcriptome." (PMID 39386562, 2024). "Irreversible mutations of many RNA binding proteins can contribute to degenerative diseases, such as mutations of TDP-43, hnRNPA1, and FUS in amyotrophic lateral sclerosis/frontotemporal dementia (ALS/FTD)." (PMID 37464880, 2023). "A dominant mutation in hnRNPA1 causes amyotrophic lateral sclerosis (ALS), but it is not known whether this mutation leads to motor neuron death through increased or decreased function." (PMID 38003404, 2023). "A number of neuromuscular and muscular diseases, including amyotrophic lateral sclerosis (ALS), spinal muscular atrophy (SMA) and several myopathies, are associated to mutations in related RNA-binding proteins (RBPs), including TDP-43, FUS, MATR3 or hnRNPA1/B2." (PMID 32292882, 2020). "Importantly, many RBPs have been shown to have strong genetic links to neurodegenerative disease; for example, mutations in TDP-43, FUS, hnRNPA1, and ATXN2 have all been shown to cause amyotrophic lateral sclerosis (ALS), frontotemporal lobar degeneration (FTLD) and/or spinocerebellar ataxia." (PMID 30068389, 2018).
amyotrophic lateral sclerosis (continued). "TDP-43 and FUS mutations are found in amyotrophic lateral sclerosis (ALS) and frontotemporal lobar degeneration (FTLD), and mutations in hnRNPA1 and hnRPNPA2/B1 have also been found in ALS." (PMID 25719440, 2015). "Our results reveal significant nuclear loss of hnRNPD, hnRNPC and hnRNPA1 in the frontal cortex of frontotemporal lobar degeneration compared to amyotrophic lateral sclerosis but not in the motor cortical neurons or Betz cells of amyotrophic lateral sclerosis cases." (PMID 39670112, 2024). "Several amyotrophic lateral sclerosis (ALS)-related proteins such as FUS, TDP-43, and hnRNPA1 demonstrate liquid–liquid phase separation, and their disease-related mutations correlate with a transition of their liquid droplet form into aggregates." (PMID 34774801, 2021). "Accordingly, recruitment of FUS, hnRNPA1 and hnRNPA2/B1 to cytoplasmic stress granules was observed in vitro and in a subpopulation of patients with the progressive neurodegenerative disease amyotrophic lateral sclerosis (ALS)." (PMID 25699204, 2015). "Additionally, some cases of PDB-like syndromes have been attributed to mutations in VCP, TNFRSF11A, TNFRSF11B, HNRNPA2B1, HNRNPA1, ZNF687 and PFN1, most of which are known to involved in the amyotrophic lateral sclerosis (ALS) and nuclear factor kappa B (NF-kB) signaling pathways." (PMID 35355568, 2022). "Indeed, changes of HNRNPA1 and HNRNPA2 expression can improve the condition of patients with amyotrophic lateral sclerosis, spinal muscular atrophy, Alzheimer’s disease, and other neurodegenerative diseases." (PMID 33907500, 2021). "These include TDP43, FUS, hnRNPA1, PSF/SFPQ and p54/NONO, all of which have been linked to neurodegeneration associated with amyotrophic lateral sclerosis and frontotemporal dementia." (PMID 29426953, 2018). "For example, as components of SGs, ATX1, hnRNPA1, TDP-43, TIA1, and TAF15 can lead to the occurrence of neurodegenerative diseases such as Alzheimer’s disease (AD), amyotrophic lateral sclerosis (ALS), and frontotemporal dementia (FTD)." (PMID 37179344, 2023).
frontotemporal dementia (34 papers, 2014 to 2026). Frontotemporal dementia (FTD) comprises a group of neurodegenerative disorders, characterized by progressive changes in behavior, executive dysfunction and language impairment, as a result of degeneration of the medial prefrontal and frontoinsular cortices. "The levels of HNRNPA1 were found dysregulated in patients with AD, and the associated genotype is likely a risk factor for frontotemporal lobar degeneration (FTLD) among the male populations." (PMID 27803687, 2016). "Several RNA-binding proteins of SGs including FUS, hnRNPA1, and TDP43 are meanwhile prone to undergo amyloid aggregation, which is closely associated with neurodegenerative diseases such as ALS and frontotemporal dementia (FTD)." (PMID 35384603, 2022). "Mutations in hnRNPA1 and hnRNPA2/B1 were recently shown to cause familial inclusion body myopathy with frontotemporal dementia, Paget's disease of bone, and ALS, and mutations in hnRNPA1 were also found in cases of sALS." (PMID 25299611, 2014). "Thus, MATR3 is among the family of genes including VCP, HNRNPA1, HNRNPA2B1 and SQSTM1 that cause “multisystem proteinopathy” associated with either one or a combination of ALS/frontotemporal dementia (FTD), VCPDM and Paget’s disease of bone." (PMID 32811564, 2020).
gastric cancer (33 papers, 2016 to 2026). A primary or metastatic malignant neoplasm involving the stomach. "Consistent with the reports that the long noncoding RNA colon cancer-associated transcript-1/miR-490 axis regulates gastric cancer cell migration by targeting hnRNPA1." (PMID 30250403, 2018). "For example, chemotoxicity-induced exosomal lncFERO regulates ferroptosis and stemness in gastric cancer stem cells through the hnRNPA1/SCD1 axis." (PMID 41601687, 2026). "Studies have shown that Ubiquitin‐Specific Protease 7 (USP7) promotes CAFs in the gastric cancer TIME to secrete miR-522–laden exosomes by regulating the deubiquitination of heterogeneous nuclear ribonucleoprotein A1 (hnRNPA1)." (PMID 40977700, 2025). "USP7 stabilize hnRNPA1 through transferring miR-522 to increase gastric cancer cells’ resistance to cisplatin treatment." (PMID 39605891, 2024). "Exo-lncFERO derived from GC cells then enters gastric cancer stem cells (GCSCs) and upregulates SCD1 expression in GCSCs by binding SCD1-associated mRNA and recruiting hnRNPA1, thereby suppressing GCSC ferroptosis and reducing chemosensitivity in GC cells." (PMID 38216595, 2024). "Taking lncRNA CCAT1 as an example, it sponges miR-490 and indirectly upregulates the expression of hnRNPA1 and subsequently facilitates hnRNPA1-mediated AS events, leading to the migration and metastasis of gastric cancer." (PMID 37215575, 2023). "For instance, it is reported that hnRNPA1 can act as an intermediate molecule to further promote the metastasis and of hepatocellular carcinoma and gastric cancer." (PMID 35814393, 2022). "Except for metabolic regulation, hnRNPA1 is also involved in the metastasis of gastric cancer, liver cancer, bladder cancer and pancreatic cancer." (PMID 35814393, 2022). "The lncRNA CCAT1 binds and sponges miR-490, which directly inhibits the expression of the SF hnRNPA1, consequently increasing hnRNPA1-mediated AS to promote gastric cancer cell migration." (PMID 33407694, 2021). "To date, the role of HNRNPA1 in ACC has not been studied, but other studies have shown that overexpression of HNRNPA1 in hepatocellular carcinoma and gastric cancer promotes tumor invasion and is related to poor prognosis." (PMID 34359790, 2021). "RP11‐81H3.2/miR‐339/HNRNPA1 interaction network regulates gastric cancer development and progession." (PMID 32052594, 2020). "Although USP7, hnRNPA1 and miR-522 are proved to be up-regulated in gastric cancer, they are also widely expressed in normal tissues." (PMID 32106859, 2020). "Results of RT-PCR showed that the exon 9 was up-regulated while exon 10 was down-regulated in si-hnRNPA1-transfected gastric cancer cells." (PMID 26745603, 2016). "miRNA-522, regulated by heterogeneous nuclear ribonucleoprotein A1 (hnRNPA1), is secreted from cancer-associated fibroblasts and packed into exosomes, leading to chemo-resistance through targeting 15-LOX and decreasing ROS accumulation in gastric cancer cells." (PMID 33868986, 2021). "However, studies have shown that HNRNPA1 is highly expressed in gastric cancer cells, thus promoting gastric cancer proliferation, invasion, migration, and EMT." (PMID 31355251, 2019). "Our data indicates hnRNPA1 directly regulates the expression of PKM2 in gastric cancer cells." (PMID 26745603, 2016). "In addition, exosomal lncFERO derived from gastric cancer cells was found to promote SCD1 expression by directly interacting with SCD1 mRNA and recruiting heterogeneous nuclear ribonucleoprotein A1 (hnRNPA1), which resulted in the suppression of ferroptosis in gastric cancer stem cells." (PMID 37686142, 2023). "Moreover, some studies have shown that miRNA-2 promoted carcinogenic activity by upregulating the expression of RAN in HCC cells; the high expression of HNRNPA1 promoted the invasion of gastric cancer cells; lncRNA CDKN2B-AS1 promoted the growth of HCC by regulating the let-7c-5p/NAP1L1 axis." (PMID 34426790, 2021).